AFP (alpha fetoprotein)
Diseases named in the same sentence as AFP in open-access papers (continued):
Sharing a sentence is not in itself a finding about the gene and the disease.
tumor (continued). "The independent risk factors for tumor recurrence were AFP/TTV >2 (HR = 1.62, 95% CI = 1.29–1.98, P = 0.042), Macrovascular invasion (HR = 2.03, 95% CI = 2.17–2.38, P = 0.021, and microvascular invasion (HR = 1.36, 95% CI = 1.08–1.77, P = 0.019)." (PMID 32426129, 2020). "IDR remains the most frequent event during the follow-up of patients treated by PTA for small HCC, and was associated with both tumor size and AFP, suggesting a metastatic mechanism." (PMID 32013112, 2020). "A Cox proportional hazard analysis showed that a history of HCC therapy, the presence of a hypovascular tumor, and AFP >4.6 ng/mL at the end of treatment were independent risk factors for HCC development." (PMID 32790728, 2020). "Increased SNRPB expression was positively associated with adjacent organ invasion, tumor size, serum AFP level and poor HCC patient survival." (PMID 33289700, 2020). "The levels were associated with age, BCLC stage, levels of AFP, tumor size, tumor number, EHM, PVTT and Child-Pugh class in the HCC cohort." (PMID 31898536, 2020). "The factors influencing survival were tumor number and size, alpha‐fetoprotein, albumin, bilirubin, vascular invasion, cause, and response as assessed by mRECIST." (PMID 31698504, 2020). "After PSM, results of multiple Cox regression analysis showed that AFP, Tumor size and Tumor number were independent risk factors for the RFS, and the Anesthetic methods and Age were independent risk factors for the OS." (PMID 31918433, 2020). "Low RDM1 expression was associated with high AFP levels, large tumor size, advanced TNM stage, and poor tumor differentiation." (PMID 31670863, 2020). "In a meta-analysis to systematically review the association between PNI and HCC prognosis, PNI was significantly associated with AFP level, tumor size and TNM stages." (PMID 33129309, 2020). "AFP values have been associated with worse clinical outcomes in patients with tumor progression during sorafenib treatment." (PMID 32492896, 2020). "Unfortunately, we only obtained other four independent risk factors, including ECOG performance status, serum AFP level more than 400 μg/L, tumor size larger than 10 cm, and PVTT status which adversely influenced oncological prognosis." (PMID 32322268, 2020). "In particular explant studies have demonstrated higher AFP levels ≥200 ng/ml are associated with higher risk of both microvascular and macrovascular invasion, along with poorly differentiated tumours as was demonstrated in our analysis." (PMID 32471447, 2020). "Our model was developed based on the vascularization pattern, ALBI grade, AFP level, γ-GT level and major tumor size, which were significant factors associated with TACE refractoriness in logistic regression model." (PMID 32489476, 2020). "Although several studies have been performed to evaluate the clinical features of patients or tumor characteristics in the cases of HCC with normal (< 20 ng/mL) serum AFP levels, the molecular mechanisms underlying this feature remain to be determined." (PMID 33371894, 2020). "The model confirmed the prognostic influence of the variables in the mHAP‐III model, namely tumor number, tumor size, AFP, albumin, and bilirubin, in addition to VI and cause." (PMID 31698504, 2020). "Multivariable analysis showed that size of the largest tumor >5cm and high alpha-fetoprotein of >200 ng/mL were significant factors associated with failure of OR to two consecutive TACE sessions." (PMID 32130270, 2020). "The prediction model of this study includes four relevant risk factors, namely, ALBI grade, maximal tumor size, baseline AFP, and initial TACE response." (PMID 32487089, 2020). "Meanwhile, many other studies have also revealed that the high concentration of AFP in patients' serum was associated with high risk of tumor recurrence/progression and reduced survival at different stages of the diseases." (PMID 32426269, 2020).
tumor (continued). "In particular, tumor-specific ctDNA methylation has been shown to outperform AFP in sensitivity and specificity as both a diagnostic and prognostic marker for HCC62." (PMID 33268834, 2020). "Univariate Cox hazards analysis showed that AJCC stages, tumor size, tumor metastasis, and AFP levels were associated with the 5-year OS rate." (PMID 32341205, 2020). "Serum AFP values above 400 ng/mL have been associated with higher waitlist tumor progression and a lower response rate after trans-arterial chemoembolization (TACE)." (PMID 32492896, 2020). "Univariate and multivariate analyses showed that AFP > 400 ng/ml, tumor size, and preoperative CTC count are independent risk factors for the presence of MVI." (PMID 33129301, 2020). "Nevertheless, increasing AFP values are associated with lower survival and higher tumor recurrence rate in patients at very early or early stages, as well as poor prognosis in patients with advanced HCC." (PMID 32492896, 2020). "There was a significant difference between the 2 groups in the preoperative total bilirubin level, serum AFP level, mean tumor diameter, TTV, operative blood loss, microvascular invasion and hospital stay (all P values < 0.05)." (PMID 32426129, 2020). "A higher NCSTN expression level was significantly associated with higher serum AFP level, tumor size as well as poorer tumor differentiation, indicating that the NCSTN was possibly correlated to HCC growth and progression." (PMID 32631394, 2020). "In this study, we investigated the effects of AFP on immune-related protein expression and NF-κB pathway (P65) activation, which elucidated the molecular association between AFP expression and tumor immunity." (PMID 32774373, 2020). "Sex, cause, tumor number, tumor size, VI, AFP, and bilirubin were found to be statistically significant prognostic variables." (PMID 31698504, 2020). "Consistent with previous findings, our data indicate that higher tumor burden (larger tumor size, multiple tumors, vascular invasion, distant metastasis, and high serum AFP level) and ascites were associated with decreased survival in patients with RI." (PMID 32366000, 2020). "It has been suggested that the secretion of AFP correlates directly to cell proliferative activity and tumor size so potentially associated with a more aggressive tumors." (PMID 32426129, 2020). "Downregulated MARC2 was significantly associated with clinicopathological characteristics of HCC, such as tumor size, AFP levels, and tumor grade and was an independent risk factor of poor prognosis." (PMID 32811980, 2020). "The analysis of the clinicopathological characteristics indicated that lower expression of MARC2 was significantly associated with larger tumor size, higher levels of AFP, and higher tumor grade." (PMID 32811980, 2020). "Along with AFP level, we found like others on multivariate analysis that markers of both hepatic reserve and tumour burden are key prognostic markers being associated with poorer survival following repeat TACE." (PMID 32471447, 2020). "The higher risk group was found to be significantly associated with higher tumor grade, higher AFP, a higher rate of vascular invasion and advanced TNM stage in the TCGA cohort." (PMID 32760210, 2020). "An exploratory univariable analysis showed that albumin, Ln(bilirubin), ECOG PS, macrovascular invasion, extrahepatic spread, largest tumour size, number of liver lesions, Ln(AFP) and receiving prior HCC treatments were associated with OS." (PMID 31579990, 2020). "In this study, tumor size, subcapsular, and AFP were the risk factors for seeding after PTA, which was consistent with the previous reports." (PMID 32702175, 2020). "A Cox proportional hazard analysis showed that a history of HCC therapy, the presence of hypovascular tumor, and an AFP >4.6 ng/mL at the end of treatment were independent risk factors for HCC development." (PMID 32790728, 2020).
tumor (continued). "The proposed nomogram considered six independent risk factors: AJCC T, AJCC M, surgery, tumor grade, AFP level and fibrosis." (PMID 33288828, 2020). "Frequencies of patients with certain clinicodemographic characteristics were stratified into groups at low or high risk of RFS; this analysis identified significant associations of the risk score with AFP, new tumor event and cancer status." (PMID 32592379, 2020). "Previous research has reported that the incidence of MVI ranged from 15 to 57% in HCC specimens and was associated with tumor size, AFP and typical imaging features." (PMID 33129301, 2020). "When survival was assessed from date of response assessment (instead of date of treatment), mRECIST response (following first TACE), cause, tumor number, tumor size, VI, AFP, and bilirubin significantly influenced prognosis." (PMID 31698504, 2020). "Different studies showed that large TTV can predispose to have AFP >400 ng/ml, AFP level has been linked with the aggressive behavior of the tumor cells and disease progression." (PMID 32368340, 2020). "A strict tumor size or number cutoff to select patients for preoperative biopsy can miss out on patients with high AFP and poor grade leading to unacceptable recurrence risk." (PMID 32787864, 2020). "All tumour biomarkers (except AFP) had significant associations with secondary end‐points (composite of all‐cause mortality and HF hospitalization, HF hospitalization, cardiovascular (CV) mortality and non‐CV mortality)." (PMID 32372544, 2020). "Clinically, phosphorylation of NF90-Ser382 is significantly associated with larger tumor sizes, higher AFP levels, and shorter overall survival rates." (PMID 32123579, 2020). "Earlier studies have shown direct association of higher AFP levels (>200 ng/ml) with tumor size, stage, and HBsAg positivity in viral-HCC." (PMID 33614488, 2020). "Despite its many limitations as a diagnostic tumour marker, it is difficult to discount AFP as a useful tool in resource poor economies like Ghana." (PMID 32774619, 2020). "Lower tumor differentiation grades, higher alpha-fetoprotein level, bigger tumor size, and higher tumor extension remained significantly associated with worse survival." (PMID 32117759, 2020). "We found that high DEPTOR levels were significantly associated with serum AFP levels (p = 0.035), tumor size (p = 0.048), vascular invasion (p = 0.020), TMN stage (p = 0.033) and BCLC stage (p = 0.048) of HCC." (PMID 31228948, 2019). "In the present study, we found that the AFP level was associated with tumor differentiation, and tumor size." (PMID 31791275, 2019). "In this cohort, a 3‐year survival was associated with BMI, antivirus treatment, tumor status, hepatic function, and AFP level." (PMID 31313476, 2019). "In order to determine unique somatic derangements associated with AFP-high tumours, HCC samples were analysed by whole-exome sequencing." (PMID 31285588, 2019). "We then evaluated the correlation of TRIS with clinicopathological variables and observed that the TRIS was statistically associated with sex (P = 0.02), AFP (P = 0.009), tumor diameter (P = 0.02), and tumor numbers (P = 0.046)." (PMID 31164128, 2019). "On the contrary, it suggested that HCC recurrence after the DAA therapy was associated with tumor‐related factors, such as high AFP level and multiple occurrences of HCC before the DAA therapy." (PMID 30900818, 2019). "We found that DEPTOR was frequently overexpressed in HCC tissues, and its high expression was associated with high serum AFP levels, increased tumor size, vascular invasion and more advanced TMN and BCLC stage, as well as an overall poor prognosis." (PMID 31228948, 2019).
tumor (continued). "Quantitative realtime polymerase chain reaction (qRT-PCR) analysis showed that the expression levels of stemness-associated genes, including OCT4 and NANOG, and tumor markers, including AFP and CK19, in HCC cells were downregulated by ATO." (PMID 31186405, 2019). "Combined CK19/GPC3 sub-typing, pre-transplant AFP level, tumor diameter and vascular invasion for novel risk score model were devised." (PMID 31676847, 2019). "In that setting, comparison of baseline characteristics showed that the patients with CPR were in fact at increased baseline risk of tumor recurrence, as indicated by a higher AFP level and a larger tumor size." (PMID 31520204, 2019). "High-risk class and alpha-fetoprotein at the Re-S-time resulted independently related to tumor recurrence after LT: HR = 2.89 (95% CI: 1.26–6.64; P = 0.012) and HR = 1.23 (95% CI: 1.10–1.37; P = 0.0002), respectively." (PMID 31142035, 2019). "Tumor size (p = 0.038), vascular invasion (p = 0.011), and AFP (p = 0.003) were independently associated with recurrence as well." (PMID 31141535, 2019). "The preoperative AFP concentration was associated with tumor load, and elevated AFP was related to postoperative HCC recurrence in several previous studies." (PMID 30728421, 2019). "Of these, with results reported as the odds ratio (95% CI), maximal diameter, ALT, AFP and tumor capsule were independently associated with MVI." (PMID 31632502, 2019). "The factors also indicated that tumor aggressive nature, such as tumor differentiation, AFP and extent of PVTT, were tightly associated with long-term survival of patients." (PMID 30886700, 2019). "The independent factors associated with MVI were ALT, AFP, tumor maximal diameter, and tumor capsule." (PMID 31632502, 2019). "On univariate survival analysis, the factors significantly associated with OS were serum AFP, tumor size, BCLC stage, TNM stage, differentiation, vascular invasion and positive expression of FBXO22." (PMID 30808376, 2019). "We suspected that the AFP elevation was caused by hepatocellular regeneration instead of tumor relapse." (PMID 31836006, 2019). "After analysis, it was shown that if the patient’s AFP value dropped by more than 60% after preoperative chemotherapy, they would have a reduced risk of tumour recurrence." (PMID 31822277, 2019). "Univariate analysis revealed that ALDH2 “GG” genotype, microvascular invasion, macrovascular invasion, higher tumor number, larger tumor size, AFP, and AST were significantly associated with a shorter time-to-distant metastasis." (PMID 31737110, 2019). "Herein, we identify a novel early recurrence related pseudogene RACGAP1P which was significantly upregulated in HCC and was associated with larger tumour size, advanced clinical stage, abnormal AFP level and shorter survival time." (PMID 31160556, 2019). "In these patients, risk factors for tumor recurrence comprised larger size of the largest tumor on explant pathology (p = 0.044), higher AFP model score (p = 0.019), longer total duration of graft ischemia (p = 0.016), and younger donor age (p = 0.041)." (PMID 31163668, 2019). "Different miRNA delivery strategies were assayed, consisting of intratumoral injection of cholesterol-conjugated miR-199a/b-3p mimics or AAV vector particles inhibiting tumor growth, decreasing AFP levels, and causing tumor necrosis." (PMID 31805631, 2019). "An orthotopic HCC xenograft model was employed to test in vivo the efficacy of a lypopoliplex (LPP)-let-7c formulation, displaying a significant reduction of tumor burden associated with decreased AFP serum levels and increased apoptotic markers." (PMID 31805631, 2019). "Cancers were identified using four independent techniques: microscopy by a trained histopathologist, and use of antibodies to Cyokeratin 7, a marker of neoplasms, Ca 19-9, a carbohydrate antigen associated with gastrointestinal cancers, and AFP." (PMID 30939854, 2019).
tumor (continued). "In HBV-negative patients, risk factors for tumor recurrence comprised longer total duration of graft ischemia (p = 0.016), higher AFP model score (p = 0.004), and younger donor age (p = 0.017)." (PMID 31163668, 2019). "High serum AFP concentration (>400 ng/mL) is associated with greater tumor size, portal vein thrombosis and poor prognosis." (PMID 31181647, 2019). "Lower ACR was associated with advanced TNM stage, larger tumor size, and a high concentration of AFP." (PMID 31164099, 2019). "Alpha fetoprotein is a useful diagnostic tumor maker of HCC that has been used for tumor staging, diagnosis, monitoring, and even detecting the recurrence of liver tumors." (PMID 31141523, 2019). "On preoperative examination, parameters like less than 1 viable tumor, less than 1 cm of tumor size, and less than 20 ng/mL of serum alpha fetoprotein were associated with PDS." (PMID 31316165, 2019). "In the validation group, 5hmC expression was associated with sex, age, the AFP level, tumour number and TNM stage." (PMID 31033072, 2019). "Many factors affect the risk of post-operative HCC recurrence, including tumor size, tumor encapsulation, microvascular invasion, liver cirrhosis, serum α-fetoprotein (AFP) level >400 μg/L and use of antiviral drugs." (PMID 31413831, 2019). "No other significant IRI effects were found in patients beyond the Up-to-7 criteria and in analyses stratified for independent risk factors for recurrence: tumour number and differentiation, alpha-fetoprotein, and microvascular invasion." (PMID 29895820, 2018). "HBV- related HCC patients with serum iron levels lower than 15.1 μmol/l was an independent risk factor together with higher AFP levels, larger tumor size, and worse BCLC stages for the survival of HCC." (PMID 29467672, 2018). "Univariate analysis showed that AFP, tumor number, lymphatic metastasis, tumor size, embolus as well as TRIM44 staining were associated with OS and cumulative recurrence." (PMID 29446253, 2018). "The authors demonstrated that the level of AFP mRNA in blood was significantly increased in association with tumor size and serum AFP concentration." (PMID 30176913, 2018). "Here we performed the first external validation of the SNACOR (tumour Size and Number, baseline Alpha-fetoprotein, Child-Pugh and Objective radiological Response) risk prediction model." (PMID 29703174, 2018). "In our analysis, we found that siglec-2 expression in tumor tissues was significantly negatively associated with AFP elevation." (PMID 30355653, 2018). "Gain of SKA1 expression was associated with higher serum AFP concentration, larger tumor size and higher TNM stage." (PMID 30537941, 2018). "Increase in lncPARP1 expression was associated with age, α-fetoprotein (AFP) levels, tumor size, recurrence, and poor prognosis of HCC patients." (PMID 29776974, 2018). "A lower LMR was significantly associated with higher values of AFP, tumor number, tumor size, PLT and AST (all P < 0.05)." (PMID 29416061, 2018). "In multivariate Cox analysis, we confirmed that King’s score, tumor size and serum alpha-fetoprotein level were independent predictors associated with recurrence." (PMID 29555927, 2018). "Angiolymphatic invasion was associated with AFP expression in tumor tissues and serum AFP levels, as found in the univariate and multivariate analysis." (PMID 30112355, 2018). "This is in agreement with the results of Penget al.20, who revealed that serum AFP correlated with tumor size and high AFP (>200 ng/dl) was associated with large tumors (>5 cm)." (PMID 30467522, 2018). "Increase in lncPARP1 expression is closely associated with age, AFP level, tumor size, and recurrence of HCC patients." (PMID 29776974, 2018). "Immunohistochemistry revealed that increased SKA1 expression was present in 65 of the 126 cases and was significantly associated with higher serum alpha-fetoprotein concentration, larger tumor size and higher TNM stage." (PMID 30537941, 2018).